PARP2 (poly(ADP-ribose) polymerase 2)
Diseases named in the same sentence as PARP2 in open-access papers (continued):
Sharing a sentence is not in itself a finding about the gene and the disease.
tumor (continued). "Some of these genes, such as KRT19, EMP1, and PARP2, have evidence from previous studies, which indicate their higher expression levels in the original tumors compared with PDX tumor cells." (PMID 29534550, 2018). "The levels of PARP2 transcripts are similar in normal and tumor samples, whereas PARP1 has on average a twofold increase in tumor samples compared to normal samples." (PMID 29259170, 2017). "Inhibiting PARP2 in siPFKFB4 100 nM, siHMOX1, and DOX alone, and its downregulation in siPFKFB4 100 nM and DOX, led to suppressed cell proliferation and improved chemotherapy potency against aggressive tumor cells." (PMID 40739397, 2025). "Similarly, the PARPi induced an increase in cell size in iNOS mRNA and, finally, the ability to kill tumor cells ex vivo in PARP1- or PARP2-null macrophages." (PMID 36223740, 2022). "In that report, the authors suggested that modest preferential radiosensitization could be observed by WEE1 and PARP2 inhibitors in the HPV− cell lines, whereas Chk1 inhibitors were more efficient in HPV+ tumor models." (PMID 36612094, 2022). "For example, PARP-1, but not PARP-2, is involved in the formation of immunosuppressive macrophage phenotypes in the tumor microenvironment after olaparib treatment and further modulate immunosuppression by enhancing PD-1 expression." (PMID 33525353, 2021). "Tumor onset was significantly delayed in PARP2 global KO and mammary KO mice, but not in myeloid KO mice, as compared to their respective WT controls." (PMID 32221289, 2020). "Cells are able to tolerate HR inhibition equally well in the presence or absence of PARP3, in keeping with the observations that AZD2461, a compound that inhibits PARP1 and PARP2 but not PARP3, effectively causes BRCA-mutated tumour regression." (PMID 29467415, 2018). "Furthermore, high PARP2 expression, but not PARP1, showed an association with right-sided tumors, late pathological tumor stages, and disease-free survival." (PMID 40573300, 2025). "The cited studies also confirm our analyses in which we showed that in tumor cells TRPM2 gene expression is significantly decreased whereas PARP1 and PARP2 expression is significantly increased, which may indicate that TRPM2 gene loses its function in tumor cells." (PMID 32423430, 2020). "Although, we note that PARP1 and PARP2 (the primary targets of PARP inhibitors) increased or remained stable throughout tumor progression, which may lead to a stable effect of PARP inhibitors across tumor stages." (PMID 32207233, 2020). "Moreover, PARP1 and PARP2 expression were lower in tumor subsets with high Aneuploidy score, although the correlation with LST and FGA did not achieve statistical significance for PARP1 and PARP2, respectively." (PMID 40573300, 2025). "This transformation is not dependent on PARP1 or PARP2 but is the result of the accumulation of the PARP substrate NAD+, which allows for increased mitochondrial RET, resulting in ROS production and reprogramming toward an anti-tumor phenotype." (PMID 36223740, 2022). "Moreover, HRD scores may not fully capture the context in which PARP1 and PARP2 protect the CRC genome against worsening genotoxic stress, nor the contexts in which their inhibition would be beneficial for tumor cell killing." (PMID 40573300, 2025).
infection (2 papers, 2017 to 2019). The state of being infected such as from the introduction of a foreign agent such as serum, vaccine, antigenic substance or organism. "However, IMPDH2 that interacts with and supplies PARP1 and PARP2 with NAD+ substrates for enzymatic reactions significantly enhances polymerase activity during infection." (PMID 31015836, 2019). "We then carried out silencing of Parp1 or Parp2 by infection with shRNA-expressing lentiviruses." (PMID 28095779, 2017).
gynecologic tumors (1 paper, 2022). "PARP2 located in chromosome 14 encodes for a class of nuclear enzymes involved in the pathogenesis of diverse gynecologic tumors." (PMID 34996381, 2022).
neurodegenerative disease (1 paper, 2020). A disorder of the central nervous system characterized by gradual and progressive loss of neural tissue and neurologic function. "Finally, PARP2 depletion is partially protective in neurodegenerative diseases that are related to the deregulation of autophagy." (PMID 32046043, 2020).
PARP2 also shares sentences with these, for which no sentence is quoted: lymphoma (3 papers); Cachexia (2); metabolic disorders (2); acute pancreatitis (1); autoimmune disease (1); B-cell lymphoma (1); bone metastasis (1); cardiovascular disease (1); colorectal cancer (1); gastric cancer (1); head and neck cancer (1); heart failure (1); ischemic stroke (1); lung adenocarcinoma (1); macrocytic anemia (1); multiple sclerosis (1); myocardial infarction (1); nasopharyngeal carcinoma (1); neutropenia (1); prostate tumors (1); Psoriasiform dermatitis (1); rectum adenocarcinoma (1).